CLCN4 (Cl-/H+ antiporter 4)
Diseases named in the same sentence as CLCN4 in open-access papers:
CLCN4 is named in the same sentence as 40 diseases in open-access papers, as found by Europe PMC text mining. Sharing a sentence is not in itself a finding about the gene and the disease. The quoted sentences say what the papers report.
epilepsy (10 papers, 2021 to 2025). A brain disorder characterized by episodes of abnormally increased neuronal discharge resulting in transient episodes of sensory or motor neurological dysfunction, or psychic dysfunction. "CLC-4 is extensively expressed in the brain, heart, liver, kidney, and intestine, CLCN4 mutations are associated with X-linked ID, epilepsy, behavior disorders, and dysmorphic features." (PMID 37671947, 2023). "Sequence variations in CLCN4 have recently been associated with X-linked intellectual disability, epilepsy, white matter abnormality, and cortical atrophy in humans." (PMID 35721313, 2022). "We here studied 12 CLCN4 variants that were identified in patients with X-linked intellectual disability and epilepsy and were already characterized to some extent in earlier work." (PMID 35721313, 2022). "In summary, we performed a detailed functional analysis of the effects of 12 CLCN4 mutations identified in patients with X-linked intellectual disability and epilepsy on ClC-4 transport, subcellular localization, and heterodimerization with ClC-3." (PMID 35721313, 2022). "Moreover, CLCN4 has been implicated in X-linked intellectual disabilities and epilepsy, with prominent focal seizures observed in some cases." (PMID 40223930, 2025). "Patients carrying the L221V mutation suffer from epilepsy and mild-moderate intellectual disability; thus, their phenotype more closely resembles those of patients with mutations that reduce Cl–/H+ exchange than those with CLCN4 loss-of-function mutations." (PMID 35721313, 2022). "The phenotypic spectrum of CLCN4-related epilepsy includes medication-resistant seizures, intellectual disabilities, behavioural disorders, and congenital anomalies." (PMID 40223930, 2025). "Currently, mutations in the CLCN1, CLCN2, CLCN3, CLCN4, and CLCN6 genes have been reported to be associated with various forms of epilepsy." (PMID 40223930, 2025). "Encoding the vesicular 2Cl−/H+ exchanger, ClC-4 is translated from the gene CLCN4, which is implicated with neurological disorders, including epilepsy and neurodevelopmental disability." (PMID 39336754, 2024). "More recently, an additional six males with CLCN4-related neurodevelopmental condition were reported confirming the core feature of ID and common comorbidities of epilepsy and challenging behaviors." (PMID 36385166, 2023). "Epilepsy is also a significant characteristic feature of CLCN4-related neurodevelopmental conditions." (PMID 37789889, 2023). "Epilepsy is also confirmed as a significant feature of CLCN4-related neurodevelopmental condition, affecting 59% of all males and 20% of females." (PMID 36385166, 2023). "However, he has significant ID, epilepsy, and autism spectrum disorder, which are atypical for Desbuquois syndrome, and thus most likely has a blended phenotype of Desbuquois dysplasia and CLCN4-related neurodevelopmental condition." (PMID 36385166, 2023).
Intellectual disability (8 papers, 2017 to 2025). "In this study, we screened 401 children with intellectual disability (ID) and identified five CLCN4 variants in six individuals, aiming to gain further insights into the clinical and genetic characteristics of MRXSRC." (PMID 37789889, 2023). "The six children with CLCN4 variants exhibited a neurodevelopmental spectrum disease characterized by intellectual disability (ID), delayed speech, autism spectrum disorders (ASD), microcephaly, hypertonia, and abnormal imaging findings." (PMID 37789889, 2023). "The six children with CLCN4 variants presented with a neurodevelopmental spectrum disease featuring intellectual disability (ID), delayed speech, autism spectrum disorders (ASD), microcephaly, hypertonia, and abnormal imaging manifestations." (PMID 37789889, 2023). "Our investigation expands the phenotype spectrum for CLCN4 variants with syndromic X-linked intellectual disability, which help to improve the understanding of CLCN4-related intellectual disability and will help in genetic counselling for this family." (PMID 34479510, 2021). "The importance of ClC-4-mediated ion transport is illustrated by the association of naturally occurring CLCN4 mutations with epileptic encephalopathy, intellectual disability, and behavioral disorders in human patients." (PMID 35721313, 2022).
Epileptic encephalopathy (5 papers, 2015 to 2023). A condition in which epileptiform abnormalities are believed to contribute to the progressive disturbance in cerebral function. "Furthermore, variations in CLCN1, CLCN2, and CLCN4 have been reported in patients with idiopathic epilepsy and epileptic encephalopathy; however, the association of some variants with disease pathogenesis is still controversial." (PMID 25794116, 2015). "The first CLCN4 variant was reported in an infant male with developmental and epileptic encephalopathy and suggested CLCN4 as a novel candidate disease gene." (PMID 36385166, 2023).
colon cancer (4 papers, 2010 to 2023). "It is likely that colon cancer metastases to the liver are associated with elevated CLCN4 expression." (PMID 37671947, 2023). "In 2010, Dr. T. Ishiguro identified CLCN4 as a promoter of colon cancer migration, invasion, and metastasis." (PMID 37671947, 2023). "In 2010, Dr. T. Ishiguro identified CLCN4 as a novel promoter of colon cancer migration, invasion, and metastasis." (PMID 37671947, 2023). "It was revealed that CLCN4 overexpression promoted cell migration, invasion, and metastases, and CLCN4 was a novel driver in colon cancer." (PMID 36246902, 2022). "We observed a clear enrichment of CLCN4 expression in colon cancer metastases to the liver for all nine patients over that evident with primary tumours." (PMID 20087350, 2010). "In conclusion, using a gene-trap strategy, we identified CLCN4 as a novel gene product that is stimulatory for colon cancer cell migration, invasion and metastases." (PMID 20087350, 2010). "Using this gene-trap system, we report herein the identification of chloride channel 4 (CLCN4) as a novel gene product that enhances colon cancer migration and metastases." (PMID 20087350, 2010). "CLCN4-overexpressing RKO colon cancer cells were more resistant than controls to proton load-induced cytotoxicity, consistent with the H+-extruding function of this antiporter." (PMID 20087350, 2010). "An elevated CLCN4 transcript level was again evident in colon cancer metastases to the lymph nodes compared with expression in the synchronous primary colon tumours." (PMID 20087350, 2010). "We describe herein gene trapping of the Cl−/H+ exchanger, CLCN4, as a novel promoter of colon cancer migration, invasion and metastases." (PMID 20087350, 2010). "If CLCN4 promotes tumour spread, a high level of expression would be predicted in liver metastases in colon cancer patients." (PMID 20087350, 2010). "Further, we show that CLCN4 expression is probably elevated in colon cancer metastases to the liver, our findings being consistent with the observation of increased mRNA levels in metastases to the lymph nodes as per a query of the GEO database." (PMID 20087350, 2010). "As to the mechanism by which CLCN4 promotes colon cancer migration, invasion and metastases, several possibilities can be entertained." (PMID 20087350, 2010). "As the region of the genome (Xp22.3) harbouring CLCN4 shows gain/amplification in 16% of colon cancer patients, we presume that CLCN4 overexpression reflects, in part, increased gene dosage." (PMID 20087350, 2010). "Similar to RKO colon cancer cells, CLCN4 overexpression also yielded an enhanced migration (P<0.05) of HCT 116 cells." (PMID 20087350, 2010). "Owing to the fact that increased CLCN4 expression augmented in vitro migration and invasion, we hypothesised that CLCN4 would increase the metastatic ability of colon cancer cells." (PMID 20087350, 2010). "Taken together, these data suggest that CLCN4 stimulates colon cancer progression." (PMID 20087350, 2010). "We verified continued overexpression of CLCN4 in colon cancer metastases to the liver by RT–PCR." (PMID 20087350, 2010). "Towards this end, we transduced LS174 colon cancer cells with lentivirus particles bearing a CLCN4 shRNA or, as a control, a non-targeting shRNA." (PMID 20087350, 2010). "Thus, the modulatory effect of CLCN4 on tumour cell migration is not restricted to RKO and LS174 colon cancer cell lines." (PMID 20087350, 2010).
X-linked intellectual disability (4 papers, 2017 to 2023). An X-linked intellectual deficiency in which not enough information is known, reported or published to indicate whether a gene causes non-syndromic or syndromic presentations. "The dysfunction of the CLCN4 gene can lead to X-linked intellectual disability and Raynaud–Claes syndrome (MRXSRC), characterized by severe cognitive impairment and mental disorders." (PMID 37789889, 2023). "Variants in CLCN4 was first dentified in five families with variable X-linked intellectual disability and seizure disorder in 2016." (PMID 34479510, 2021). "Relatively unknown disease associated genes such as Clcn4 (X-linked intellectual disability) are among the many that are solely suppressed in dying neurons." (PMID 28751711, 2017).
glioma (2 papers, 2010 to 2019). A benign or malignant brain and spinal cord tumor that arises from glial cells (astrocytes, oligodendrocytes, ependymal cells). "Although, to our knowledge, this is the first report of a causal role for CLCN4 in tumour progression, an earlier study is relevant for showing that pharmacological blockade of chloride channels was shown to reduce glioma cell migration and invasion into foetal rat brain aggregates." (PMID 20087350, 2010).
neuropathies (2 papers, 2021 to 2025). "Activating CLCN7 mutations can cause vacuolization in patients’ tissues, but it is unclear whether this occurs in CLCN3 or CLCN4 neuropathy patients whose mutations we have analyzed here." (PMID 40169677, 2025).
Anxiety (1 paper, 2025). Intense feelings of nervousness, tension, or panic often arise in response to interpersonal stresses. "Our findings indicate that the PHIP mutation is primarily responsible for core psychological and behavioral symptoms, such as anxiety and depression, while the CLCN4 mutation, by causing brain atrophy, exacerbated the severity of the disorder." (PMID 41383545, 2025). "The PHIP mutation was associated with core neuropsychiatric symptoms, including anxiety and depression, whereas the CLCN4 mutation contributed to severe brain atrophy observed in neuroimaging, further exacerbating cognitive and behavioral deficits." (PMID 41383545, 2025).
Brain atrophy (1 paper, 2025). Partial or complete wasting (loss) of brain tissue that was once present. "A notable aspect of this case is the CLCN4 mutation, which significantly affected brain structure, particularly causing brain atrophy, as seen in MRI images." (PMID 41383545, 2025).
breast adenocarcinoma (1 paper, 2020). "Other potentially altered loops include a CTCF site near BCL6 in hepatocellular carcinoma and breast adenocarcinoma, and CLCN4 in colorectal adenocarcinomas." (PMID 32024999, 2020).
endometrial carcinoma (1 paper, 2023). A malignant tumor arising from the epithelium that lines the cavity of the uterine body. "The objective of this study was to explore the potential pathogenic role of CLCN4 in endometrial carcinoma (UCEC) with a better understanding of the pathological mechanisms involved." (PMID 37671947, 2023). "Immunohistochemical experiment was used to verify the expression of CLCN4 in endometrial cancer tissues and normal tissues." (PMID 37671947, 2023). "There are some signs that CLCN4 may be related to the evolution of endometrial cancer, according to the findings." (PMID 37671947, 2023).
endometrial tumors (1 paper, 2023). "Our results indicated that downregulation of CLCN4 exerted an inhibitory effect on endometrial tumor proliferation and migration." (PMID 37671947, 2023). "Immunohistochemical experiment reveals that CLCN4 is high expressed in endometrial tumors, in vitro experiment reveals that knockdown of CLCN4 inhibits the cells proliferation, migration and invasion." (PMID 37671947, 2023).
lung carcinoma (1 paper, 2012). "In addition, knockdown of FLJ20420 expression also significantly increased the expression of PRKCBP2, TGFBR1, TGFB2, CLCN4, TRAF3, MYLK and ACTA2, while decreasing the expression of SMAD5 and prot-LBC, resulting in an increased apoptotic potential in FLJ20420-silenced lung cancer cells." (PMID 22567091, 2012).
Obesity (1 paper, 2025). Accumulation of substantial excess body fat. "In TNBC tumors of AA patients with obesity, seventeen miRNAs, seven of which (miR-195-5p, miR-130a-3p, miR-130a-5p, miR-424-5p, miR-148a-3p, miR-374-5p, and miR-30a-5p) potentially downregulated two or more genes (e.g., CLCN4, PLCB1, CDC25B, AEBP2, ERBB4)." (PMID 41009685, 2025).
polycystic kidney disease (1 paper, 2021). A usually autosomal dominant and less frequently autosomal recessive genetic disorder characterized by the presence of numerous cysts in the kidneys leading to end-stage renal failure. "As shown in the previous studies, expression of two ion transport proteins, Pkd2 (Polycystic kidney disease 2, TPM: 20.6) and Clcn4 (H+/Cl– exchange transporter 4, TPM: 9.5), were found in the current transcriptome." (PMID 34803745, 2021).
retinal degeneration (1 paper, 2022). Degeneration of the retina. "Clcn3E281Q/E281Q/Clcn4–/– animals had an inflammatory response in the DHSC and early onset hippocampal and retinal degeneration, illustrating the importance of ClC-3 Cl–/H+ transport for neuroglia function and neuronal integrity in supraspinal brain regions." (PMID 37124866, 2022). "Clcn4–/– mice do not exhibit hippocampal or retinal degeneration." (PMID 37124866, 2022).
cancer (3 papers, 2010 to 2023). A tumor composed of atypical neoplastic, often pleomorphic cells that invade other tissues. "Cancer cases were split into two groups based on the expression level of CLCN4, high expression, and low expression." (PMID 37671947, 2023). "For the majority of cancer types, there was a significant correlation between CLCN4 expression and immune cell infiltration, especially CD4+ T cells." (PMID 37671947, 2023). "There are several possible mechanisms to explain why elevated CLCN4 promote cancer cells migration, invasion, and metastasis." (PMID 37671947, 2023). "Results revealed that high expression of CLCN4 was observed in 20 cancer types of TCGA." (PMID 37671947, 2023). "The connections between CLCN4 and the five DNA methyltransferases were assessed, DNMT3A had significantly negatively correlation in 21 cancers." (PMID 37671947, 2023). "The negative connection between CLCN4 and T cell CD4+ Th1 in most cancers shows that CLCN4 may have a potential immunological mechanism." (PMID 37671947, 2023).
neurological disorders (3 papers, 2021 to 2025). "Since activating mutations in CLCN3 and CLCN4 are associated with neurological disease, we expect to find T9 CID mutations in nervous system disorders." (PMID 40169677, 2025). "This suggests an involvement of ClC-4 in neuronal differentiation, which may contribute to the neurological disorders in patients with CLCN4 mutations." (PMID 33708769, 2021).
tumor (2 papers, 2010 to 2023). "PTEN (57%), PIK3CA (48%), TIN (44%), and CLCN4 (6%), together with other genes with the highest mutation rates in the two groups, are displayed in the tumor’s abscissa in." (PMID 37671947, 2023). "Using the public database TCGA, we analyzed the pathogenic genes of each tumor, and found a significant correlation between CLCN4 gene expression and survival, immune infiltration, and genetic instability, particularly in UCEC." (PMID 37671947, 2023). "Finally, and reminiscent of our findings with CLCN4, expression of the ether a go-go (Eag1) potassium channel is linked with tumour metastases, in that its expression correlates with lymphatic node metastases and organ metastases." (PMID 20087350, 2010). "We evaluated the relationship between CLCN4 expression levels and mutation levels in the 10 MMR genes to ascertain CLCN4’s potential role in tumor progression." (PMID 37671947, 2023). "To verify the expression of CLCN4 in UCEC, we treated tumor and normal tissues with IHC and found that CLCN4 were highly expressed in UCEC." (PMID 37671947, 2023). "It is necessary to perform in vivo experiments to determine the mechanism through which CLCN4 promotes tumor growth." (PMID 37671947, 2023). "According to the TCGA, CLCN4 expression increased with tumor stage in LUAD, TGCT, and THCA in stage II, and stage III increased in TGCT, however decreased in stage IV in KIRC." (PMID 37671947, 2023). "Then, a comprehensive analysis was conducted on CLCN4 to investigate its pathogenic mechanism in UCEC, and cell experiments confirmed that it weakens tumor proliferation, migration and invasion." (PMID 37671947, 2023). "To answer this question, we cultured RKO cells overexpressing CLCN4, or the vector only, in an acidic medium akin to the pH evident in the tumour microenvironment." (PMID 20087350, 2010). "We therefore assayed CLCN4 transcript levels in a small series of resected human primary tumours and liver metastases." (PMID 20087350, 2010). "CLCN4 was substantially expressed in UCEC tumor tissues when compared to normal tissues (p < 0.01)." (PMID 37671947, 2023). "The CCLE database was then used to demonstrate CLCN4 expression in various tumor cell lines." (PMID 37671947, 2023). "Several studies have reported the role of CLCN4 in tumor progression." (PMID 37671947, 2023). "Thus, to validate the gene-trapped CLCN4 as an inducer of tumour cell migration, the following experiments were performed." (PMID 20087350, 2010). "Indeed, our unpublished findings that the general chloride channel inhibitor attenuated the effects of CLCN4 overexpression on tumour cell migration is in agreement with this contention, notwithstanding the caveat that this blocker targets other chloride channels as well." (PMID 20087350, 2010). "Although we cannot rule out the possibility of a CLCN4 signal from the liver itself, the tumour cellularity of the metastatic lesions was estimated to be >80%, making this possibility less likely." (PMID 20087350, 2010).
neurodevelopmental disorder (1 paper, 2025). A behavioral and cognitive disorder with onset during the developmental period that involves impaired or aberrant development of intellectual, motor, or social functions. "Variants in CLCN3 and CLCN4, encoding the neuronal endosomal Cl−/H+ antiporters ClC-3 and ClC-4, are linked to neurodevelopmental disorders with broad phenotypic variability." (PMID 41439993, 2025). "Variants in both CLCN3 and CLCN4 are associated with neurodevelopmental disorders that share partially overlapping but distinct symptom profiles." (PMID 41439993, 2025).
CLCN4 also shares sentences with these, for which no sentence is quoted: behavior disorders (3 papers); autism spectrum disorder (2); mental disorder (2); channelopathies (1); Cognitive impairment (1); colorectal adenocarcinoma (1); depression (1); Desbuquois dysplasia (1); Desbuquois syndrome (1); genetic diseases (1); glioblastoma (1); hepatocellular carcinoma (1); Hypertonia (1); Klinefelter syndrome (1); microcephaly (1); neuroblastoma (1); Neurodevelopmental delay (1); Seizure (1); X linked intellectual disability syndrome (1); X-linked chondrodysplasia punctata (1).